MMP9 (matrix metallopeptidase 9)
Diseases named in the same sentence as MMP9 in open-access papers (continued):
Sharing a sentence is not in itself a finding about the gene and the disease.
tumor (continued). "This suggests that the recruitment of inflammatory monocytes by the primary tumor, followed by macrophages, is instrumental in the upregulation of MMP9 expression within the pre-metastatic lung niche." (PMID 39317708, 2024). "GBM patients exhibiting elevated levels of MMP9 in tumor tissue or peripheral blood exhibited a notably poorer survival outcome, which is consistent with our results." (PMID 38214842, 2024). "Specifically, MMP-2 and MMP-9 are pivotal in degrading basement membrane type IV collagen, thereby promoting tumor growth, invasion, and angiogenesis." (PMID 39431222, 2024). "It was found that the MMP-2 and MMP-9 levels in tumor tissue, epinephrine and norepinephrine levels in serum, and the tumor volume were significantly higher in the stressed group than in the non-stressed group." (PMID 39335164, 2024). "MMP-9 also contributes to angiogenesis and tumor progression by releasing VEGF-A and inhibiting anti-angiogenic molecules." (PMID 38533507, 2024). "MMP9 is a key player in various critical processes such as tissue disruption, tumor neovascularization, and subsequent metastasis." (PMID 39480853, 2024). "Except for tumorigenic and metastatic hepatocytes, only the component of MMP9+ macrophage showed increasing in the Pro-Meta group across three cohorts consistently, indicating the heterogeneity of tumor microenvironment composition among patients." (PMID 38824541, 2024). "CCL2 then activates MAPK signaling in tumor cells and increases tumor cell migration and MMP-9 expression." (PMID 39555068, 2024). "MMP-9 is a key neutrophil protease that remodels the extracellular matrix to trigger an “angiogenic switch” and promotes tumor invasion and angiogenesis." (PMID 39795864, 2024). "IHC results illustrated that MMP2 and MMP9 expression in tumor tissue was suppressed by Oct4 knockdown." (PMID 38430256, 2024). "Through this analysis, we elucidated the interactions between MICA+ tumor cells and MMP9+ macrophages, primarily mediated via the PROS1-AXL axis in advanced HCC." (PMID 38254761, 2024). "As such, several studies have already found a significant association between MMP-1, MMP-2, MMP-9, and MMP-13 expression and tumor development, as well as aggressiveness and fast metastatic pattern." (PMID 39063046, 2024). "Targeting the activity of MMP9 has been shown to have beneficial effects in reducing tumor growth and metastasis." (PMID 38560573, 2024). "Increased MMP-9 expression in the tumor microenvironment (TME) plays a crucial role in the extracellular matrix remodeling to facilitate cancer invasion and metastasis." (PMID 39351229, 2024). "Alterations in the ECM mediated by MMP9 lead to substantial architectural modifications within the tumor stroma, resulting in a desmoplastic reaction." (PMID 39664453, 2024). "Elevated MMP9 levels correlate strongly with lymph node metastasis and higher Dukes' stages, indicating its significant role in tumor invasion and metastasis." (PMID 39664453, 2024). "To further elucidate the intricate interplay between MICA+ HCC cells and MMP9+ macrophages, we conducted a meticulous analysis of scRNA-seq data derived from tumor samples." (PMID 38254761, 2024). "Remarkably, the shICAM1 group exhibited significantly reduced p-JNK and MMP9 expression in tumor cells." (PMID 38907234, 2024). "Immature myeloid cells (iMCs) are recruited from the bone marrow to the tumor invasion front express matrix metalloproteinases MMP9, MMP2, and CCR1, migrating toward the Ccl9 expressed by the tumor epithelium in adenocarcinoma." (PMID 39768150, 2024). "The Her2 protein is a prevalent clinical marker for malignant tumors and is often accompanied by the upregulation of matrix metalloproteinase (mmp)-2 and mmp-9, thereby promoting tumor proliferation and metastasis." (PMID 39198434, 2024).
tumor (continued). "Histamine and heparin released by MCs impede tumor cell growth in certain malignancies, and MCs also enhance tumor invasion and angiogenesis by secreting chymotrypsin, trypsin, matrix metalloproteinase 9 (MMP-9), and VEGF." (PMID 38898505, 2024). "The invasion and metastasis of tumor cells are intricately regulated by the ECM, with MMPs, particularly MMP2 and MMP9, playing a crucial role in facilitating tumor formation and metastasis by degrading matrix proteins." (PMID 39759103, 2024). "Studies have found that matrix metalloproteinase-9 (MMP-9) plays a significant role in cancer cell invasion, metastasis, and tumor growth." (PMID 38240894, 2024). "MMPs are a family of ECM enzymes that facilitate the invasion of tumor cells, and among them MMP9 is perceived as a key regulator for tumor angiogenesis induced by PMN-MDSCs." (PMID 38520006, 2024). "Some clusters expressed a combination of markers associated with tumor proliferation and invasiveness, such as CD44, S100A4, CD74 and MMP-9 (Tumor 7, 29.1%, n=8; range 0.7-81.5% per PDAC)." (PMID 39575252, 2024). "Curcumin has been reported to inhibit NF-κB expression and the activity of MMP-2 and MMP9, thereby suppressing tumor metastasis and invasion." (PMID 38313314, 2024). "Single-cell sequencing on primary bone cancer revealed that the ERK5/MMP9 pathway promotes cancer cell proliferation, colony formation, migration, tumor growth, and lung metastasis, with the RNA interference silencing of ERK5 mitigating these effects." (PMID 38785963, 2024). "Subjecting these transplanted niches to surgical resection via biopsy punch enhanced CD31, MMP9, Ly6G, and tumor burden compared to control scaffolds." (PMID 39149496, 2024). "MYC likewise can control the expression of the tumour-promoting factors: matrix metallopeptidase 9 (MMP9), VEGF, TGF-β and HIF-1 (Ref." (PMID 39320855, 2024). "Collectively, these findings indicated that VM in EBV-related tumour cells can be promoted by the secretion of MMP9 from M2c-like macrophages." (PMID 39267775, 2024). "This was associated with the downregulation of NFκB target genes, including VEGF‐C and MMP‐9, probing the involvement of the NFκB in driving tumor progression." (PMID 39617741, 2024). "In both animal groups, the expression of MMP-2 and MMP-9 genes was significantly decreased in tumor tissues, while the TIMP-1 and TIMP-2 genes were overexpressed." (PMID 39335164, 2024). "The same was observed for mmp2 and mmp9, metalloproteases connected to tumor cell invasion, for glucose-phosphate isomerase 1 (gpi1), tnfα, lysyl oxidases (lox, loxl), and the progenitor marker cd44 that is also linked to increased metastasis." (PMID 39095583, 2024). "In line with a hyperresponsiveness to VEGF, we observed a substantial increase in MMP9 levels in CD93-deficient subcutaneous tumors and lung metastases, which was associated with enhanced invasion and improved colonization of tumor cells." (PMID 38441970, 2024). "In IL-6 knockout mice, tumor growth and formation were downregulated, and proliferation markers and MMP-9 were reduce." (PMID 38438872, 2024). "When MMP9 was combined with tumor volume, multivariable logistic regression identified the combination as an excellent biomarker (AUCMMP9+vol = 0.91, Sensitivity 75%, Specificity 96%)." (PMID 38887507, 2024). "Specifically, we explored the potential interaction between MICA+ tumor cells and MMP9+ macrophages." (PMID 38254761, 2024). "MMP-9 plays a specific function in tumor cell invasion and the progression of primary tumors through its involvement in extracellular matrix (ECM) remodeling." (PMID 39769318, 2024). "Elevated expression of MMP1, MMP2, MMP3, MMP7, MMP9, MMP13, and MMP14 has been consistently associated with tumor progression, metastasis, and a less favorable prognosis." (PMID 38939095, 2024).
tumor (continued). "As gelatinases, MMP-2 and MMP-9 degrade type IV collagen in the basement membrane, contributing to carcinogenic processes such as cell proliferation, angiogenesis, and tumor metastasis when their activity is dysregulated." (PMID 39063556, 2024). "The interaction between MICA+ tumor cells and MMP9+ macrophages was mediated through the PROS1-AXL pathway." (PMID 38254761, 2024). "Endogenous MMP inhibitors such as Thrombospondin-1 (TSP-1) regulate MMP-2 and MMP-9 activity reducing tumor growth in pre-clinical tumor models." (PMID 38659022, 2024). "Activation of the interferon gamma (IFN-γ) signaling pathway was observed in MICA+ tumor cells and MMP9+ macrophages." (PMID 38254761, 2024). "In contrast, N2-TANs, which are induced by TGF-β, promote tumor growth and participate in tumor migration and metastasis by upregulating arginase, MMP-9, VEGF, and additional chemokines." (PMID 39877377, 2024). "We observed endothelial cells with MMP-9 immunoexpression, particularly in areas where glomeruloid structures were present in the tumor stroma (arrows)." (PMID 39684754, 2024). "On the other hand, MMP-2 expression was correlated with tumor size and neovascularization, MMP-9 expression was correlated with hormone receptor status, and stromal cell co-expression of MMP-2 and MMP-9 was significantly associated with tumor size." (PMID 37496657, 2023). "Tumour-derived EVs were taken up by astrocytes and led to increased MMP9 secretion through activation of the JNK pathway, but with no clear difference between the radiation and control experiments." (PMID 37798728, 2023). "Western blot experiments further showed that the expression levels of the tumor metastasis markers, matrix metallopeptidase 9 (MMP9) and MMP2, were decreased significantly in C918 cells after TAP1 silencing." (PMID 36774490, 2023). "In another hand, M2 neutrophils facilitate tumor growth through expressing arginase, MMP-9, VEGF and multiple chemokines." (PMID 36855112, 2023). "This condition explains that MMP-9 contributes only a few parts of the tumor progression and generally works with other molecules together to regulate the tumors." (PMID 37175113, 2023). "The diminished production of VEGF and matrix metalloproteinase 9 (MMP-9) further reduces the incidence of tumor dissemination." (PMID 37460927, 2023). "CAF expression of MMP11, MMP2, MMP9, and MMP21 in various malignancies is associated with a significant risk of tumor relapse." (PMID 38035101, 2023). "The increased MMP-2, MMP-9 and waveform proteins, as well as the decreased E-calmodulin in tumor cells, tend to promote the process of epithelial–mesenchymal transition (EMT), thus favoring tumor expansion into adjacent tissues." (PMID 37367063, 2023). "Previous studies have shown that bFGF contributes to increased invasiveness of tumor cells by enhancing the ability of fibroblasts to produce various growth factors such as TGFβ1 and matrix metalloproteinase (MMP-9)." (PMID 38152616, 2023). "During tissue remodeling, MMP9 can cause the degradation of gelatin and collagen types IV, V, XI, and XVI, which are essential for tumor invasion and metastasis." (PMID 36412203, 2023). "Further, Matrix metalloproteinase 9 (MMP-9) induced in tumor microenvironments contribute to tumor progression and metastases." (PMID 37514190, 2023). "The increase in MMP-9 expression in tumor tissues plays a vital role in realizing the metastatic process’s sequential phases." (PMID 36837487, 2023). "The sequential delivery of CA4-NPs and MMP9-DOX-NPs increased tumor-selective drug release by amplifying MMP9 expression and enhanced antitumor efficacy with a tumor inhibition rate of 88.2%." (PMID 37415158, 2023). "A previous study showed that SNAI1 expression is regulated by the secretion of MMP9 to induce EMT during tumor cell invasion." (PMID 37190063, 2023).
tumor (continued). "Among these, MMP-2 is expressed most frequently when tumor cells undergo invasive behavior, while MMP-9 is expressed most frequently when tumor cells undergo metastatic behavior." (PMID 36976205, 2023). "We also demonstrated that MMP-9 induction originates from BMSCs through direct cell contact with tumor cells." (PMID 36674806, 2023). "MMP9 is essential for angiogenesis and expansion of tumor lesions in pancreatic cancer, and both are mediated through MMP-regulated degradation of basement membrane and extracellular matrix, as well as release of matrix-bound growth factors." (PMID 37638028, 2023). "Meanwhile, the expression of PCNA, VEGF, MMP‐2 and MMP‐9 was dramatically reduced in tumour‐bearing mice treated with PA in comparison with the vehicle group." (PMID 37038620, 2023). "Silencing of AKR1B10 in these tumor cells downregulated MMP2 and MMP9 expression, suppressing both in vitro and in vivo tumor cell extravasation across the BBB." (PMID 37688612, 2023). "MMP9 plays an irreplaceable role in tumor initiation and progression, including tumor angiogenesis, promotion of tumor growth, and destruction of the basement membrane to promote tumor metastasis and spread." (PMID 37978381, 2023). "MMP9 is one of the essential extracellular matrix proteases, whose role in tumor metastasis processes is well known." (PMID 36687217, 2023). "The suppression of these signaling pathways also decreased MMP2 and MMP9 expressions, which are the critical markers of tumor metastasis." (PMID 37367670, 2023). "Recently, it has been shown in CRC that tumor-infiltrating neutrophils are able to suppress T cell function via secretion of the Matrix Metalloproteinase 9 (MMP9), which, in turn, activates latent TGF-β." (PMID 37511431, 2023). "Research has established that MMP-2 and MMP-9 foster tumor invasion and metastasis through collagen degradation, leading to extracellular matrix disruption and consequent cellular dysfunction." (PMID 37881489, 2023). "A positive association between MMP9 and lymph node metastasis and pathological TNM staging demonstrates MMP9 as a potential biomarker to predict the behavior of the tumor." (PMID 36756017, 2023). "cRGD-lipo-LGAL nanoparticles effectively inhibited TAK1 phosphorylation and MMP9 expression, suppressing tumor growth and lung metastasis in TNBC." (PMID 37041137, 2023). "IHC examination of tumor sections showed that LINC00665_18aa expressing tumors had markedly fewer cells stained for MMP9 staining than the controls." (PMID 37285335, 2023). "Specifically, upon injection of 5T33MMvt cells into immature mice, MMP-9 secretion was upregulated in MM cells isolated from the BM (5T33MMvt-vv) during tumor development." (PMID 37823051, 2023). "Specifically, MMP9 is known to play a crucial role in the degradation of type IV collagen in the basal membrane surrounding the tumor, thereby promoting tumor cell infiltration and metastasis." (PMID 37509716, 2023). "Vahid Haghpanah discovers that VPA, as a histone deacetylase inhibitor, reduces the expression of MMP-2 and MMP-9, declines stem cell markers and tumor aggressiveness, and stimulates the anaplastic thyroid cancer cells to redifferentiate." (PMID 37175113, 2023). "In particular, the activation of c-Jun augments MMP9 and Bcl-2 expressions, bolstering the tumor’s proliferation and metastatic potential." (PMID 38140058, 2023). "Age and gender analyses were carried out in the control group, eliminating the possible MMP-9-modifying effect of any tumour disease." (PMID 36765669, 2023). "Sanz Moreno showed that MMP9 regulates amoeboid migration in a catalytic independent manner through regulation of actomyosin contractility via CD44 receptor in tumor cells." (PMID 36759828, 2023). "On the other hand, IL-1β enhances tumor invasiveness and aggression by decreasing E-cadherin expression and inducing MMP-9." (PMID 38248096, 2023).
tumor (continued). "In the middle and late stages of tumor development, MMP-9 can also promote the expression of VEGF to promote invasion and metastasis in blood vessels." (PMID 38067451, 2023). "Daniel Buergy detects that increasing levels of MMP-9 are consistent with the metastasis of the tumor and the tumor recurrence locally, which indicates its predictive relevance to tumor progression and prognosis." (PMID 37175113, 2023). "The expression of matrix metalloproteinase-9 (MMP-9) and chemokine receptor 7 (CCR7) is significantly associated with tumor invasion and metastasis." (PMID 37600570, 2023). "In more detail, the gelatinase MMP-9 is crucial for ECM degradation in tumor invasion, metastasis, and angiogenesis and is directly linked to a poor prognosis in CRC patients." (PMID 36982752, 2023). "The protein expression levels of MMP-2 and MMP-9, which are proteins that indicate tumor invasiveness, were found to decrease in ezetimibe-treated groups." (PMID 36843944, 2023). "For instance, exosomal FasL derived from T cells has been shown to promote invasion and metastasis of Fas + tumor cells by increasing the expression of MMP9." (PMID 37670933, 2023). "Studies have shown that MMP9 is involved in various biological processes such as tumor invasion, metastasis, angiogenesis, and tumor microenvironment." (PMID 37644107, 2023). "E‐cadherin, N‐cadherin and Vimentin are essential proteins involved in EMT, while MMP‐9 is a critical protein in tumour proliferation." (PMID 37859585, 2023). "Specifically, it has been reported that MMP-7 contributes to tumor invasion, proliferation, and antiapoptotic potential in CRC, while MMP-9 has been implicated in extracellular protein proteolysis during tumor invasion in CRC." (PMID 36901174, 2023). "These axes not only lead to neutrophil recruitment but also participate in tumor promotion by activating neutrophils to increase the expression of pro-tumor factors like MMP-9 from neutrophils." (PMID 37333017, 2023). "For example, MMP-9, besides degrading collagen type IV, the primary component of the basement membrane, promotes tumor invasion and angiogenesis by proteolytically activating TGF-β." (PMID 37266453, 2023). "CHI3L1 also induces the expression of pro-tumorigenic molecules, including CXCL2, MMP-2, and MMP-9, which contribute to tumor growth and proliferation." (PMID 37480002, 2023). "MMP2 and MMP3 can degrade multiple components of basement membrane and extracellular matrix, and MMP9 is able to induce tumor cells to infiltrate and metastasize into adjacent normal tissues through the injured basement membrane." (PMID 37100464, 2023). "An increase in the levels of MMP-2 and MMP-9 has been described in the irradiation of various tumours." (PMID 38203696, 2023). "Through the remodeling of the extracellular matrix, MMP-2 and MMP-9 are involved in tumor invasion and metastasis." (PMID 37516013, 2023). "The high expression of MMP-2 and MMP-9 in cancerous tissues has been correlated with tumor cell matrix degradation, invasion, and migration." (PMID 37964204, 2023). "In oral squamous cell carcinoma (OSCC), knockdown of MMP9 lead to inhibition of cell migration, proliferation, interactions between endothelial cells, tumor growth of nude mouse xenografts, angiogenesis, and OSCC cell metastasis to mouse lymph nodes." (PMID 36677584, 2023). "Several studies have also reported that MMP-9 is responsible for a wide range of tumour activities, the majority of which encourage the growth and spread of cancer cells." (PMID 37600570, 2023). "Our data show similar results to previous research, showing that ALC downregulates the expression of MMP9, which likely suppresses the in vitro hallmarks of tumor progression by inhibiting adhesion, migration, and invasion of four prostate cell lines." (PMID 36975525, 2023).